LINC01278 (long independently transcribed non-coding RNA 1278)
Gene: Long non-coding RNA gene on chromosome X (63,222,993 to 63,561,095, reverse strand). Ensembl gene ENSG00000235437.
Diseases named in the same sentence as LINC01278 in open-access papers:
LINC01278 is named in the same sentence as 3 diseases in open-access papers, as found by Europe PMC text mining. Sharing a sentence is not in itself a finding about the gene and the disease. The quoted sentences say what the papers report.
pulmonary diseases (1 paper, 2022). "These genes include the long non-coding gene LINC01278 and some other genes known to be involved in the interferon network but lacking understanding of their role in pulmonary diseases, such as IDO1 and BTN3A2." (PMID 36203777, 2022).
tumor (2 papers, 2021 to 2022). "These two latest studies suggest that the role of LINC01278 in tumor cells may depend on the specific tumor types, tumor microenvironment, or downstream targets." (PMID 35498540, 2022). "The role of LINC01278 in tumor cells may depend on the specific tumor types, tumor microenvironment or downstream targets." (PMID 34273985, 2021).
cancer (1 paper, 2022). A tumor composed of atypical neoplastic, often pleomorphic cells that invade other tissues. "LINC01278, an oncogene in other cancers, has been found related to clinical staging, distant metastasis, and poor prognosis of patients." (PMID 35498540, 2022).